MALAT1 (metastasis associated lung adenocarcinoma transcript 1)
Diseases named in the same sentence as MALAT1 in open-access papers (continued):
Sharing a sentence is not in itself a finding about the gene and the disease.
lymph node metastasis (42 papers, 2015 to 2025). "High MALAT1 levels were significantly associated with clinical stage (p = 0.009), histological grade (p = 0.002), and lymph node metastasis (p = 0.011) in HNC patients." (PMID 40150019, 2025). "Further analyses using the datasets from The Cancer Genome Atlas (TCGA) revealed that lower MALAT1 mRNA levels were associated with the advanced stage, and lymph node metastasis in LADC patients." (PMID 38517388, 2024). "The over-expression of MALAT1 is also associated with lymph node metastasis in several forms of cancers." (PMID 36934373, 2023). "Our results indicated that MALAT1 SNP rs619586 is positively associated with advanced Gleason grade, while rs1194338 plays a part in lymph node metastasis, especially in patients with iPSA >10 ng/mL." (PMID 34574033, 2021). "Not only cancer progression, but also tumor size, lymph node metastasis, and shorter overall survival of cancer patients were found to be associated with MALAT1 up-regulation." (PMID 31792655, 2020). "For instance, the MALAT1 expression level was associated with lymph node metastasis and poor survival rate of UCC patients." (PMID 30813594, 2019). "For example, metastasis-associated lung adenocarcinoma transcript-1 (MALAT1) was reported to associate with lymph node metastasis and poor overall survival." (PMID 30813594, 2019). "Pooled result showed that high expression of MALAT1 was significantly associated with lymph node metastasis, suggesting that MALAT1 can serve as a valuable biomarker for predicting lymph node metastasis status." (PMID 29899709, 2018). "The results revealed that high MALAT1 expression was significantly associated with lymph node metastasis (OR = 2.731; 95% CI: 1.409–5.292; p = 0.003)." (PMID 29899709, 2018). "This meta-analysis aimed to examine the association between deregulated MALAT-1 expression and lymph node metastasis of multiple cancers." (PMID 26989678, 2016). "This meta-analysis collected all relevant articles and explored the association between MALAT-1 expression levels and lymph node metastasis." (PMID 26989678, 2016). "In this present study, we further verified that overexpression of MALAT1 is associated with the incidence of lymph node metastasis in many types of cancer." (PMID 27777857, 2016). "Moreover, subgroup analysis of cancer type presented that patients with MALAT1 over-expression had higher risk of lymph node metastasis and distant metastasis." (PMID 30093838, 2018). "As revealed in subgroup analysis, the incidence of lymph node metastasis in Chinese cancer patients had significance associated with MALAT-1 high expression (OR: 1.58, 95% CI: 1.01–2.46), while cancer patients in Japan show no significant result (OR: 1.52, 95% CI: 0.46–5.05)." (PMID 26989678, 2016). "Therefore, we conducted a systematic review and quantitative meta-analysis to clarify the exact diagnostic value of MALAT-1 expression association with lymph node metastasis in human cancers." (PMID 26989678, 2016). "Clinical investigations have further demonstrated that increased MALAT1 levels correlate with larger tumor size, lymph node metastasis, and poorer overall survival among cancer patients." (PMID 39319867, 2025). "In both laboratory and animal studies, it has been demonstrated that MALAT1 is notably increased in CRC and is linked to more advanced TNM staging, lymph node metastasis, and a worse prognosis for patients." (PMID 39830506, 2024). "High MALAT1 levels were associated with an advanced TNM stage and lymph node metastasis in CRC patients." (PMID 33344634, 2020). "MALAT-1 expression is strongly correlated to lymph node metastasis (P = 0.007) and clinical stage (P = 0.007)." (PMID 30352575, 2018). "The result showed that MALAT1 expression was significantly correlation with local invasion, lymph node metastasis and TNM stage." (PMID 28396617, 2017).
lymph node metastasis (continued). "In this study, we demonstrated MALAT1 was up-regulation in GC tissues compared with adjacent normal tissues and higher MALAT1 expression was correlated with local invasion, lymph node metastasis and TNM stage." (PMID 28396617, 2017). "The results found that the incidence of lymph node metastasis was higher in high MALAT1 expression group than that in low MALAT1 expression group (pooled OR = 1.67, 95 % CI 1.30–2.15)." (PMID 27777857, 2016). "Our analysis combined the outcomes of 696 cancer patients from 8 individual studies, indicating that MALAT-1 high expression significantly predicted a high incidence of lymph node metastasis in cancer patients (OR 1.94, 95% CI 1.15–3.28)." (PMID 26989678, 2016). "This study demonstrated that the incidence of lymph node metastasis in patients detected with high MALAT-1 expression was higher than that in patients with low MALAT-1 expression in China." (PMID 26989678, 2016). "Expression of MALAT-1 lncRNA was enhanced in TSCCs, especially in those with lymph node metastasis (LNM)." (PMID 27586393, 2016). "The results indicated a significant relation between MALAT-1 high expression and lymph node metastasis, which was also exhibited in China (OR: 1.58, 95% CI: 1.01–2.46)." (PMID 26989678, 2016). "In high MALAT1 expression group, 393 patients (49.2 %) with cancer had lymph node metastasis, while only 405 patients (50.8 %) in low MALAT1 expression group." (PMID 27777857, 2016). "Subgroup analysis indicated that MALAT-1 high expression had an unfavorable impact on lymph node metastasis in Chinese patients (OR = 1.87, 95% CI 1.01–2.46)." (PMID 26989678, 2016). "The results showed that the incidence of lymph node metastasis was higher in high MALAT1 expression group than that in low MALAT1 expression group (OR = 1.67, 95 % CI 1.30–2.15)." (PMID 27777857, 2016). "This meta-analysis was conducted to investigate the effects of MALAT1 on cancer prognosis and lymph node metastasis." (PMID 27777857, 2016). "Enhanced MALAT1 expression levels were positively correlated with clinical stages, primary tumor size, and lymph node metastasis." (PMID 25613496, 2015). "Notably, higher MALAT-1 expression is observed in poorly differentiated tumors and those with lymph node metastasis." (PMID 38511067, 2024). "To clarify whether MALAT1 could be a therapeutic target for HNSCC in vivo, we evaluated the potential clinical efficacy of MALAT1 depletion using a mouse model of lymph node metastasis." (PMID 36813772, 2023). "MALAT1 expression was significantly higher in epithelial OC patients than in controls, and it was associated with an advanced International Federation of Gynecology and Obstetrics (FIGO) stage, a high histological grade, and lymph node metastasis." (PMID 37007117, 2023). "A previous meta-analysis concluded that the overexpression of MALAT1 could predict lymph node metastasis in various types of cancer (pooled OR = 2.34, CI = 1.61–3.40, p < 0.001)." (PMID 34574033, 2021). "In contrast to the betel quid-chewing subgroup, OSCC patients with at least one T allele of MALAT1 rs3200401 were at a lower risk for developing lymph node metastasis if they did not chew betel nuts." (PMID 34268119, 2021). "In addition, high levels of exosomal MALAT1 were associated with late FIGO stage, high histological grade, and lymph node metastasis, suggesting that serum exosomal MALAT1 is associated with late and metastatic EOC behavior." (PMID 34804970, 2021). "The results demonstrated that over-expression of MALAT1 may predict lymph node metastasis (pooled OR = 2.335, 95% CI 1.606–3.395, P = 0.000) and distant metastasis (pooled OR = 2.456, 95% CI 1.407–4.286, P = 0.002)." (PMID 30093838, 2018). "In conclusion, the study revealed that over-expression MALAT1 might be an adverse biomarker for prognostic outcome, lymph node metastasis, distant metastasis, tumour size and TNM stage for cancer patients." (PMID 30093838, 2018).
lymph node metastasis (continued). "The present findings demonstrated that MALAT1 may be a novel biomarker for predicting survival outcome, lymph node metastasis and distant metastasis." (PMID 30093838, 2018). "It has been suggested that MALAT-1 expression may play a useful prediction role in the incidence of lymph node metastasis in some tumors." (PMID 26989678, 2016). "Of 360 high MALAT-1 groups, 211 patients with different cancers had lymph node metastasis (58.6%)." (PMID 26989678, 2016). "This meta-analysis explored that elevated MALAT1 expression is common to various types of cancer and might act as a novel predictive factor of poor prognosis and lymph node metastasis in different type of cancer." (PMID 27777857, 2016). "This meta-analysis revealed that elevated MALAT1 expression may serve as a novel predictive biomarker for poor survival and lymph node metastasis in different types of cancer." (PMID 27777857, 2016). "And, to some extent, overexpression of MALAT-1 was inclined to lymph node metastasis." (PMID 26989678, 2016). "In addition, MALAT1 have being related with lymph node metastasis in CRC patients." (PMID 31632922, 2019). "Moreover, upregulation of MALAT1 has been found in CRC tissues with lymph node metastasis." (PMID 31632922, 2019). "However, in low MALAT-1 group, there were only 105 patients with lymph node metastasis (31.3%)." (PMID 26989678, 2016). "The high expression of MALAT1 could be considered a biomarker of the early detection of lymph node metastasis and predictor of poor survival in RCC patients, who likely manifested short overall survival (OS; hazard ratio [HR], 2.97; 95% CI, 1.68-5.28; p<0.001)." (PMID 27527868, 2016). "Therefore, it is possible that our results might overestimate the prognostic effects of abnormal MALAT1 expression on survival and lymph node metastasis in different types of cancer." (PMID 27777857, 2016). "According to the study conducted by Zhang and colleagues, MALAT-1 expression was elevated in CRC patients, and it exhibited correlations with a poorer prognosis, lymph node metastases, and an advanced TNM stage." (PMID 38511067, 2024). "The expression level of MALAT1 is significantly increased in CRC patients and is related to advanced TNM stage, lymph node metastasis, and short survival." (PMID 36248422, 2022). "In this study, we demonstrated that MALAT1 was amplified and correlated with an advanced TNM stage, lymph node metastasis, and worse prognosis in CRC patients." (PMID 33344634, 2020). "Through comparing the incidence of lymph node metastasis between high MALAT-1 expression group and low MALAT-1 expression group, we found that there was a significant difference in the incidence of lymph node metastasis between the two groups." (PMID 26989678, 2016). "The results revealed there was a significant difference in the incidence of lymph node metastasis between high MALAT-1 expression group and low MALAT-1 expression group (OR = 1.94, 95% CI 1.15–3.28, P = 0.013 random-effects model)." (PMID 26989678, 2016). "MALAT1, an exosome-derived lncRNA that promotes cancer cell migration and prevents cancer cell apoptosis, was found to be positively related to the TNM stage and lymph node metastasis in NSCLC." (PMID 37007117, 2023). "Subgroup analysis on other factors comprising detection method did not alter the significant incidence of lymph node metastasis impact of MALAT-1 high expression." (PMID 26989678, 2016). "Furthermore, RCCRT1, SPRY4-IT1, NBAT-1, MALAT1, and ATB might be used as biomarkers of lymph node metastasis." (PMID 27527868, 2016). "In TSCC tissues with lymph node metastasis (LNM), the expression levels of MALAT-1 lncRNA were statistically higher than those without LNM." (PMID 27586393, 2016).
esophageal squamous cell carcinoma (40 papers, 2015 to 2024). Esophageal squamous cell carcinoma (ESCC) is a type of esophageal carcinoma (EC) that can affect any part of the esophagus, but is usually located in the upper or middle third. "MALAT1 has been implicated in various malignancies and confers radiosensitivity, including gastric cancer, cervical cancer, and esophageal squamous cell carcinoma." (PMID 32947897, 2020). "MALAT1 overexpression was associated with a decreased survival rate and MALAT1 can be used as a potential therapeutic target for human esophageal squamous cell carcinoma." (PMID 28388588, 2017). "Furthermore, the polymorphism rs3200401 C > T in the MALAT1 gene was recently reported to be associated with an increased risk of esophageal squamous cell carcinoma (ESCC) in a Chinese population." (PMID 31500187, 2019). "One study on Kazakh’s esophageal squamous cell carcinoma investigated the interaction between MALAT-1 and TGF-β1." (PMID 38201661, 2024). "For example, Malat1 can promote esophageal squamous cell carcinoma (ESCC) by modifying the ATM-CHK2 pathway." (PMID 39363237, 2024). "The predicted top five lncRNAs are MALAT1, MEG3, BCYRN1, UCA1, and LSINCT5, among which MALAT1 and MEG3 are found to be associated with esophageal squamous-cell carcinoma in lncRNADisease in 2017." (PMID 35186029, 2022). "The up-regulation of MALAT1 contributes to the proliferation and metastasis in esophageal squamous cell carcinoma." (PMID 31792655, 2020). "Different studies reported that MALAT1 is overexpressed in Esophageal squamous cell carcinoma (ESCC)." (PMID 29739426, 2018). "In esophageal squamous cell carcinomas, MALAT1 functions as a competing endogenous RNA (ceRNA) to sequester miRNAs." (PMID 30131454, 2018). "In esophageal squamous cell carcinoma cells, miR-217 inhibits proliferation, migration, and invasion by targeting long noncoding RNA MALAT1 and kallikrein 7 (KLK7)." (PMID 28437471, 2017). "Several mechanisms of action of MALAT1 in esophageal squamous cell carcinoma have been elucidated." (PMID 34234858, 2021). "The lncRNA MALAT1, which is overexpressed in esophageal squamous cell carcinoma (ESCC) and glioma, promotes tumor proliferation and metastasis capacity, and the lncRNA Sox2ot promotes hepatocellular carcinoma cell metastasis and is correlated with a poor prognosis." (PMID 27248828, 2016). "Moreover, a negative correlation between MIR101 or MIR217 and MALAT1 was previously observed in esophageal squamous cell carcinoma, while knockdown of MALAT1 inhibited cell growth, migration, and invasion." (PMID 27458156, 2016). "However, the roles of MALAT1 in esophageal squamous cell carcinoma(ESCC), and the mechanisms involved in cell cycle regulation remain poorly understood." (PMID 25613496, 2015). "MALAT1 functions as an apoptotic inhibitor in the context of esophageal squamous cell carcinoma (ESCC), thereby inhibiting miR-590-3p and boosting migration, cell proliferation, epithelial-mesenchymal transition (EMT), and invasion." (PMID 39323624, 2024). "Metastasis-Associated Lung Adenocarcinoma Transcript 1 (MALAT1) is a long noncoding RNA (lncRNA) that contributes to the invasion and metastasis of tumors, including esophageal squamous cell carcinoma (ESCC)." (PMID 33123280, 2020). "The upregulation of MALAT1 is related to cancer cell proliferation and metastasis and the malignant development of esophageal squamous cell carcinoma (ESCC)." (PMID 33102238, 2020). "Furthermore, Ago2-dependent post-transcriptional regulation of MALAT1 by miR-101 and miR-217 significantly impaired proliferation, migration, and invasion of Esophageal Squamous Cell Carcinoma Cells (ESCC) cells, highlighting the MALAT1-dependent tumor suppressor role of these miRNAs." (PMID 29739426, 2018). "There is evidence of a posttranscriptional regulation of MALAT1 by miR-101 and miR-217 in esophageal squamous cell carcinoma (ESCC) cells." (PMID 29147648, 2017).
esophageal squamous cell carcinoma (continued). "MALAT1 serves as an oncogene in esophageal squamous cell carcinoma (ESCC), and it regulates ESCC growth by modifying the ATM-CHK2 pathway." (PMID 27782152, 2016). "However, in contrast, others have reported minimal methylation alterations at the CpG island in the MALAT1 promoter of esophageal squamous cell carcinoma tissues and concluded that CpG island methylation status may not contribute to MALAT1 dysregulation." (PMID 29695738, 2018).
Hyperglycemia (40 papers, 2014 to 2025). An increased concentration of glucose in the blood. "Several studies found that hyperglycemia causes a significant upregulation of Lnc-MALAT1 level in retinal endothelial cells and diabetic retinas and that silencing of MALAT1 decreases retinal vascularization, vascular leakage and retinal inflammation." (PMID 37762249, 2023). "Atorvastatin protects podocytes via the metastasis-associated lung adenocarcinoma transcript 1 (MALAT1)/miR-200c/nuclear factor-erythroid 2-related factor 2 (NRF2) signaling pathway from hyperglycemia (HG)-induced pyroptosis and oxidative stress." (PMID 36204129, 2022). "Long noncoding RNA (lncRNAs) metastasis–associated lung adenocarcinoma transcript 1 (MALAT1) has been reported in diabetic nephropathy (DN) about its effect on podocyte function and cell heat shock induced by hyperglycemia." (PMID 33995063, 2021). "Previous studies also reported that upregulated expression of lncRNA MALAT1 was linked to hyperglycemia-induced inflammation and endothelial dysfunction, diabetic nephropathy, and gestational diabetes mellitus." (PMID 30139387, 2018). "We found that hyperglycemia causes a significant upregulation of lnc-MALAT1 level in retinal endothelial cell and diabetic retinas." (PMID 25356875, 2014). "Metastasis-associated lung adenocarcinoma transcript 1 (MALAT1) is a widely expressed lncRNA that was demonstrated to induce damage to micro- and macrovascular damage through alterations in its expression driven by hyperglycemia." (PMID 40100371, 2025). "We show that plasma levels of MALAT1 are associated with hyperglycemia in vulnerable CAD patients." (PMID 37569451, 2023). "MALAT1 increased with hyperglycemia and was also implicated in islet beta cell dysfunction." (PMID 35058920, 2021). "The hyperglycemia status enhances Sp1 binding at the MALAT1 promoter and elevated lncRNA MALAT1, enhances the binding of Sp1 at the Keap1 promoter, and activates its transcription." (PMID 38158644, 2024). "They found that the expression of MALAT1 was upregulated in the retinas of oxygen-induced retinopathy mice and hyperglycemia-stimulated hRMECs and that the expression of miR-203-3p was decreased." (PMID 37762249, 2023). "This study essentially showed that the downregulation of GRP78 by MALAT1 knockdown attenuated hyperglycemia (HG)-induced angiogenesis and inflammation in human RVECs." (PMID 37762249, 2023). "Meanwhile, other studies have shown that MALAT1 can be upregulated under hyperglycemia through multiple pathways." (PMID 36827547, 2023). "Recent data show that hyperglycemia increases Sp1 binding at the MALAT1 promoter in retinal microvasculature, thus increasing Lnc-RNA MALAT1 expression." (PMID 37762249, 2023). "The fact that miR-205 was reduced by the high-glucose treatment indicates that EMT can be induced via this MALAT1/miR-205 pathway under hyperglycemia condition in keratinocytes." (PMID 36827547, 2023). "After using a knockdown of MALAT1 in HaCaT cells, we then explored the role of MALAT1 in hyperglycemia-induced EMT." (PMID 36827547, 2023). "The objective of the current study is to explore the role of MALAT1 in hyperglycemia (HG)-induced EMT." (PMID 36827547, 2023). "MALAT1 has also been shown to regulate hyperglycemia-induced inflammatory processes in endothelial cells, and inhibition of MALAT1 down-regulates resistin to reduce insulin resistance by exercise." (PMID 35163020, 2022). "In situ hybridization findings showed high levels of MALAT1 expression in the cytoplasm of DPCs cultured for 14 days after hyperglycemia mineralization." (PMID 36035997, 2022). "Many studies demonstrate that the various diseases, from hyperglycemia to cancers, have a close relationship with MALAT1." (PMID 36163080, 2022).